FAM230D (family with sequence similarity 230 member D)
Synonyms: AC008079.1; formerly LINC02592
Gene: Long non-coding RNA gene on chromosome 22 (18,178,026 to 18,205,991, reverse strand). Ensembl gene ENSG00000187979.
Diseases named in the same sentence as FAM230D in open-access papers:
FAM230D is named in the same sentence as 2 diseases in open-access papers, as found by Europe PMC text mining. Sharing a sentence is not in itself a finding about the gene and the disease.
FAM230D shares sentences with these, for which no sentence is quoted: cancer (1 paper); gastric cancer (1).